RRM2 (ribonucleotide reductase regulatory subunit M2)
Diseases named in the same sentence as RRM2 in open-access papers (continued):
Sharing a sentence is not in itself a finding about the gene and the disease.
tumor (289 papers, 2004 to 2026). "RRM2 has been reported to be upregulated in many types of cancer and has been implicated in tumor progression, including NSCLC." (PMID 40636359, 2025). "It has been pointed out in the literature that RRM2 is involved in DNA synthesis and repair, and its high expression is often closely associated with cell cycle acceleration and high proliferation of tumor cells." (PMID 41333212, 2025). "Our findings indicate that the up-regulation of RRM2 mediated by ncRNAs is associated with poor prognosis and tumor immune infiltration in LUAD patients." (PMID 41357570, 2025). "The expression of RRM2 in both HVECsand tumor cells was significantly reduced, which is associated withthe action of palmatine, further confirming the treatment’sefficacy." (PMID 40834268, 2025). "RRM2 is a key ferroptosis regulator, and RRM2 inhibition has been associated with the induction of ferroptosis and tumor immune infiltration." (PMID 40630134, 2025). "The results indicated that RRM2 expression levels were significantly correlated with the immune infiltration of various tumor-associated cells in 24 tumor types." (PMID 38635758, 2024). "In this study, we demonstrated that pan-cancer RRM2 expression levels correlated with the immune infiltration levels of diverse tumor-associated cells." (PMID 38635758, 2024). "RRM2 expression is associated with the infiltration of diverse immune and endothelial cells, immune checkpoints, tumor mutational burden (TMB), and microsatellite instability (MSI)." (PMID 38635758, 2024). "Receiver operating characteristic curve analysis showed a higher diagnostic ratio for NSCLC using RRM2 alone compared to other traditional tumor markers." (PMID 37699023, 2023). "RRM2 expression was enhanced with the advancement of tumor stage and tumor grade, suggesting that RRM2 was associated with the progression of ccRCC." (PMID 36747047, 2023). "Upregulation of RRM2 has been associated with tumor angiogenesis, metastasis, progression, as well as poor prognosis of patients." (PMID 38124207, 2023). "High expression of RRM1 and RRM2 was notably associated with high tumor grade, high stage, short overall survival, and disease-specific survival." (PMID 36713030, 2023). "GO, KEGG, and GSEA analyses revealed that the biological process of RRM2 was associated with the regulation of carcinogenic processes and immune pathways in a variety of tumor types." (PMID 36518297, 2022). "RRM2 was positively related to immune checkpoints, tumor mutation burden, microsatellite instability, neoantigen, and cytotoxic T lymphocyte in several cancers, predicting effective response to immunotherapy." (PMID 35740608, 2022). "The relationship with immune cells showed that RRM2 was associated with tumor infiltration by B cells and Neutrophils." (PMID 35898471, 2022). "Concurrently, RRM2 expression was significantly associated with worse prognosis and tumor stage across TCGA cancers." (PMID 35740608, 2022). "The tumour‐promoting feature of RRM2 is associated with inducing activities of various oncogenes, including those encoding nuclear factor‐κB, Myc proto‐oncogene protein, tyrosine‐protein kinase transforming protein Fes and ornithine decarboxylase." (PMID 35757968, 2022). "The clinical data indicated that circ_0008460 and RRM2 were associated with tumor growth and metastasis, while miR-197-3p exhibited anti-tumor function in CC patients." (PMID 35609310, 2022). "In our study, we extracted the transcriptomic matrix and pathological features of BRCA samples from the TCGA database and found that RRM2 expression was associated with tumor metastasis by multivariate Cox regression." (PMID 36678539, 2022). "Previous studies concurred that increased RRM2 activity was tightly associated with tumor progression and malignancy." (PMID 35740608, 2022). "Our results revealed RRM2 as a promising biomarker and therapeutic target associated with tumor immune infiltration in patients with LUAD." (PMID 36153508, 2022).
tumor (continued). "RRM2 has been identified as an oncogene in CC and associated with anti-tumor roles of miRNAs, such as miR-140-3p and miR-5095." (PMID 35609310, 2022). "RRM2 expression level seems to associate with tumor grade, and RRM2 has been proposed as a biomarker for diagnosis and prognosis." (PMID 34895038, 2021). "The results indicated that enhanced RRM2 expression was significantly associated with advanced tumor stage and high-grade tumor, suggesting in turn a positive correlation between RRM2 expression and poor prognosis in KIRC." (PMID 33686951, 2021). "Ribonucleotide reductase subunit M2 (RRM2) has been reported in many types of cancer and has been implicated in tumor progression." (PMID 34319001, 2021). "RRM2 is known to be associated with tumor invasion and with the establishment of a metastatic phenotype, which promotes poor overall and progression-free survival." (PMID 32348423, 2020). "High expression of RRM2 was significantly associated with tumor stage (IV vs. I: OR = 3.02, p = 0.012) and TNM classification (T2 vs. T1: OR = 1.88, p = 0.001; N2 vs. N0: OR = 2.69, p < 0.001)." (PMID 33411689, 2020). "Nevertheless, RRM2 still had potential association with the regulation of the stromal cells, tumor cells and lymphocyte infiltration." (PMID 32922202, 2020). "The level of RRM2 was positively correlated with tumor grade and size, and strongly associated with poor patient outcome." (PMID 28556483, 2017). "Our data imply that elevated RRM2 expression may be associated with a subdued anti-tumor immune response." (PMID 41357570, 2025). "Furthermore, the molecular mechanism underlying RRM2’s tumor-promoting function was preliminarily investigated through mRNA sequencing and subsequent experiments." (PMID 41333212, 2025). "RRM2 governs nucleotide metabolism in tumor cells and is associated with multiple cancers." (PMID 38635758, 2024). "Interestingly, half of the genes analyzed, namely, BIRC5, TOP2A, PLK1, and RRM2, were associated with lung-specific neoplasms." (PMID 39596028, 2024). "We then analyzed the correlation between RRM2 expression levels and the immune infiltration of different tumor-associated cells (B cells, plasma cells, T cells, NK cells, monocytes, macrophages, dendritic cells, mast cells, eosinophils, and neutrophils) and their subtypes in tumors." (PMID 38635758, 2024). "The role of RRM2 in the onset and progression of multiple cancers has been examined in terms of genetic changes at the molecular level, including tumor mutational burden (TMB), microsatellite instability (MSI), biological pathway changes, and the immune microenvironment." (PMID 38635758, 2024). "In summary, our first pan-cancer analysis of RRM2 revealed statistical correlations between RRM2 expression and clinical prognosis, genetic alterations, tumor mutational burden, microsatellite instability, immune cell infiltration, and immune checkpoints across multiple tumors." (PMID 38635758, 2024). "Moreover, we explored the correlation between RRM2 expression and tumor mutational burden (TMB) and microsatellite instability (MSI) in all TCGA cancers." (PMID 38635758, 2024). "Upregulation of RRM2 was tightly associated with HB prognosis and tumor cell proliferation." (PMID 36882565, 2023). "Lastly, for the group of upregulated genes in HCC, RRM2 has also been linked with low overall survival, leading to exhaustive cancer research suggesting targeting its inhibition for different types of tumour treatments." (PMID 37438763, 2023). "RRM2 aberration may lead to genome instability and increased mutation rates, thus influencing tumor progression." (PMID 35740608, 2022). "RRM2 has been reported in various types of cancer and has been implicated in tumor progression." (PMID 35360870, 2022). "The expression of miR-582-3p was negatively associated with RRM2 expression in HCC tumor samples." (PMID 35609318, 2022).
tumor (continued). "On the basis of this hypothesis, we selected LIHC as a representative tumor for future trials to validate the carcinogenicity of RRM2 and its association with HBV as well as immune infiltration." (PMID 36518297, 2022). "RRM2 deficiency also significantly suppressed tumor growth in C57BL/6 xenograft tumor model." (PMID 33858512, 2021). "RRM2 deficiency increased CD8 + T cells in the tumor tissues and spleens." (PMID 33858512, 2021). "Importantly, expression of exogenous WT, K30Q, K61Q, or K283Q restored tumor growth in the RRM2-deficient xenografts." (PMID 31324785, 2019). "In addition, a growing body of evidence is showing that RRM2 is overexpressed in cancer and is associated with neoplasia, metastatic potential, and poor prognosis in human cancers." (PMID 26675256, 2016). "In addition, increased RRM2 activity is associated with malignant transformation and tumor cell growth." (PMID 27551518, 2016). "Thus, we investigated RRM2 genetic mutations in human tumor samples." (PMID 36518297, 2022). "RRM2 showed significant risk in univariate analyses (HR = 1.291, 95% CI = 1.150-1.450, p-value = 0), and multivariate analyses (HR = 1.255, 95% CI = 1.112-1.415, p-value = 0), indicating it can predict tumor outcomes independently of the other six immune cells." (PMID 33123291, 2020). "Molecular docking results indicated that seven known anti-tumor natural products exhibit significant binding affinity with RRM2." (PMID 41970950, 2026). "The CIBERSORT algorithm was utilized to analyze RRM2's regulatory role in the PCa tumor microenvironment, complemented by pan-cancer analysis to investigate RRM2's universal functions across various malignancies." (PMID 41970950, 2026). "Before treatment, the tumor already has pre-resistant subclones (such as those carrying RRM2 copy number gain, low dCK expression, or activated DNA repair pathways)." (PMID 41293424, 2025). "The hsa-muir-20a-5p regulator suppresses tumor angiogenesis in NSCLC by targeting the RRM2-mediated PI3K/Akt signaling pathway." (PMID 40014586, 2025). "Recent research has indicated that berberine hydrochloride and lncOCMRL1 silencing affect tumor cell metastasis by regulating RRM2 to inhibit EMT." (PMID 40732324, 2025). "Palmatine serves as a DNA intercalator and RRM2 inhibitor,disrupting cellular repair pathways in both tumor and endothelialcells." (PMID 40834268, 2025). "The correlation analysis between RRM2 expression and immune cell infiltration revealed a complex and multifaceted interaction within the tumor immune microenvironment of LUAD." (PMID 41357570, 2025). "Inhibition of RRM2 can reduce RRase activity, inhibit cancer cell growth, promote cancer cell apoptosis, prevent tumor metastasis and reverse drug resistance." (PMID 41333212, 2025). "As an essential metal cofactor for RRM2, iron plays a key role in the metabolism, proliferation and growth of tumor cells." (PMID 40510157, 2025). "It is a proprietary nanoparticle formulation targeted at the transferrin receptor, containing non-chemically modified small interfering RNA (siRNA) against the M2 subunit of ribonucleotide reductase (RRM2), with potential anti-tumor activity." (PMID 39968416, 2025). "This leads tomore severe DNA damage in both endothelial and tumor cells, furtherreducing RRM2 expression and diminishing the chances of self-repairin tumor and heterogeneous endothelial cells." (PMID 40834268, 2025). "RRM2 expression levels were found to escalate with advancing tumor stage (Kruskal-Wallis test, p=2.273×10-33), and correlated strongly with TNM-T classification (p=1.08×10-31), suggesting its role in metastatic progression." (PMID 41357570, 2025).
tumor (continued). "At the same time, proliferative markers such as MKI67, TOP2A, PRC1 and RRM2 underscore the importance of cell-cycle dynamics not only in tumor growth but also potentially within rapidly expanding immune subsets that contribute to treatment efficacy." (PMID 40745034, 2025). "Western blot analysis showed that sh-circASH1L accelerated the cisplatin-induced reduction of GPX4 and SLC7A11 expression, as well as the downregulation of CDCA7 and RRM2 in tumor tissues." (PMID 40630134, 2025). "We observed a significant decrease in miR-30a-5p expression and a significant increase in RRM2 expression in tumor tissues with HCG18 overexpression." (PMID 40303288, 2025). "RRM2, serving as the smaller subunit of ribonucleotide reductase, has been acknowledged as both a promoter of tumor growth and a viable target for cancer therapy." (PMID 39248068, 2025). "In gene therapy, CALAA-01 (cyclodextrin-based siRNA nanoparticles, phase I) silenced RRM2 in melanoma with 21% tumor reduction at 0.6 mg/kg, confirming target engagement via RISC loading assays." (PMID 41480332, 2025). "TPX2, CENPA and RRM2 showed the strongest association with elevated PSA levels, particularly in the > 4 ng/mL group, indicative of higher tumor burden and poorer prognosis." (PMID 41402347, 2025). "Silencing RRM2 inhibits PC cell proliferation and tumor growth by inactivating the PI3K/AKT/mTOR pathway, leading to cell cycle arrest and/or apoptosis." (PMID 41200180, 2025). "Since RRM2 has also been found to be a risk factor for DFS in THCA, we further validated its effects on THCA tumor cells in vitro and in vivo." (PMID 41333212, 2025). "Our integrated multi-omics analysis revealed that RRM2 is significantly up-regulated in LUAD tissues compared to normal counterparts, with a progressive increase in expression associated with advanced tumor stages and TNM classification." (PMID 41357570, 2025). "By directly suppressing tumor growth while inhibiting the proliferationof heterogeneous endothelial cells, RRM2 targeting can enhance osteosarcomatherapy." (PMID 40834268, 2025). "For example, the codelivery of RRM2 siRNA with doxorubicin or adriamycin has demonstrated superior tumor suppression in HCC." (PMID 40493217, 2025). "This up-regulation of RRM2 is consistent with its known role in promoting cell proliferation and DNA synthesis, which are critical for tumor growth and metastasis." (PMID 41357570, 2025). "In numerous cancer types, RRM2 is frequently overexpressed or amplified, providing support for tumor proliferation, survival, and genomic instability." (PMID 41439111, 2025). "The expression of RRM2 was significantly related to age, race, tumor stage, and status in nearly one-third of the TGCA." (PMID 38635758, 2024). "We assessed the correlation between the expression of RRM2 and the clinical characteristics of patients with pan-cancer, including age, race, tumor stage, and status." (PMID 38635758, 2024). "We also evaluated the correlation between the expression levels of lncOCMRL1 and RRM2 by ISH in tumor tissue samples." (PMID 39343925, 2024). "The compound COH29 has demonstrated significant inhibitory action against the RRM2 enzyme and has exhibited promising outcomes in phase I clinical trials as an anti-tumor agent." (PMID 39256879, 2024). "In a parallel manner, we noted a consistent pattern of RRM2 expression in an animal model featuring hepatic in situ xenograft tumor." (PMID 39256879, 2024). "In agreement, a systematic meta-analysis of publicly available microarray data revealed that, among other nucleotide biosynthetic enzymes, RRM2 was upregulated in human tumours." (PMID 39206868, 2024). "The F4L-deleted VVs are highly attenuated in normal tissues, but since cancer cells often express elevated RRM2 levels and have elevated levels of dNTPs, these viruses exhibit tumor-selective replication and then cell killing." (PMID 39339888, 2024).
tumor (continued). "The mouse tumor model of HCC was established by the intraperitoneal injection of H22 cells to assess the tumorigenic effect of RRM2 in vivo." (PMID 39766842, 2024). "To estimate the correlation between RRM2 expression and pan-cancer prognosis, we divided the tumor cases into two groups based on high and low expression levels of RRM2." (PMID 38635758, 2024). "Silencing RRM2 in iCCA cells significantly reduced several tumor malignancy features in vivo and in vitro." (PMID 39243109, 2024). "For example, DHS (trans-4,4’-dihydroxystilbene) suppresses DNA replication and tumor growth by inhibiting RRM2 expression in pancreatic, ovarian, and colorectal cancer." (PMID 38635758, 2024). "Studies have shown that the RRM2 gene and its promoter region are highly amplified in cancer, resulting in elevated transcription levels, and RRM2 is recognized as a promoter of tumor growth and drug resistance." (PMID 38894712, 2024). "In light of this rationale, we conducted an investigation into the genetic alterations of RRM2 within tumor samples of HCC." (PMID 39256879, 2024). "Clinical data such as age, race, sex, tumor stage, and status were acquired to analyze the influence of RRM2 on the clinical characteristics of the patients." (PMID 38635758, 2024). "In each group, membrane RRM2-positive cells formed tumor more effectively and quickly than RRM2− cells, and the tumor size in the RRM2+ group was always significantly larger than RRM2− cells." (PMID 39243109, 2024). "ISH and IHC were performed to assess the expression of lncOCMRL1, RRM2 and Ki67 in tumor tissues, and the expression of these factors was significantly decreased in the NPs(siOCMRL1) group." (PMID 39343925, 2024). "The quantitative data revealed that both RRM2 cell membrane staining and its cytoplasm staining were significantly higher in iCCA tumor cells compared to the corresponding bile duct cells and hepatocytes (P < 0.05 for each comparison)." (PMID 39243109, 2024). "This study found that in cancer types with over 12 tumor and para-cancer tissues, the genes RRM2, TK1, CCNB1, DLGAP5, CCNA2, MYBL2, and HJURP were repeatedly overexpressed across various cancer tissues." (PMID 39669580, 2024). "Using bioinformatic analysis of the Oncomine and TCGA public databases, we demonstrated that the expression of RRM2 in up to 19 tumor tissues was higher than that in the corresponding normal tissues." (PMID 38635758, 2024). "RRM2 silencing significantly delayed the tumor onset time, and decreased the rate of tumor occurrence as well as tumor size." (PMID 39243109, 2024). "RRM2 also promotes tumor angiogenesis through regulating expression of proangiogenic factor VEGF and antiangiogenic factor TSP-1." (PMID 38992695, 2024). "The cell membrane staining of RRM2 in iCCA tumor tissues was even stronger than its cytoplasm staining." (PMID 39243109, 2024). "This helped us to understand the role of RRM2 in tumorigenesis from the perspective of clinical tumor samples." (PMID 38635758, 2024). "RRM2 facilitates DNA replication and repair by supplying dNTPs through participating in the RR catalytical process, further promoting tumor cell proliferation." (PMID 38785515, 2024). "The PCR analysis revealed statistically significant higher RRM2 expression in tumor tissues compared to PT." (PMID 40625451, 2024). "The molecular mechanism of LUC7L3 promoting tumor cell proliferation, the relationship between LUC7L3 and RRM2, and its potential diagnostic and therapeutic value need to be further clarified." (PMID 38785515, 2024). "Highlighting the potential relevance of this in cancer biology, low dUTPase and high RRM2 expression in tumours correlates with poor prognosis in patients with colorectal cancer." (PMID 39206868, 2024).